ABCG2 (ATP binding cassette subfamily G member 2 (JR blood group))
Diseases named in the same sentence as ABCG2 in open-access papers (continued):
Sharing a sentence is not in itself a finding about the gene and the disease.
gastric cancer (continued). "In conclusion, after validation of commercially available ABCG2 antibodies, we established scoring guidelines for semi-quantitative measurement of ABCG2 in FFPE CRC tissue, based on the clinically used guidelines for HER2 assessment in gastric cancer." (PMID 27257141, 2016). "The preliminary results of the present study demonstrated that under hypoxic conditions, when 5-Fu was used to treat human gastric cancer cell lines, the expression of cancer stem cell markers HIF-2α and ABCG2 increased." (PMID 25452783, 2015). "Similarly, in gastric cancer, it contributes to OXP-resistance via the HOTAIR/miR-195-5p/ABCG2 axis, where the lncRNA HOTAIR acts as a ceRNA to sponge miR-195-5p, thereby upregulating ABCG2 expression and promoting OXP-resistance in cancer cells." (PMID 39401197, 2024). "In this study, we investigated whether cisplatin-increased mitROS production in gastric cancer cell lines (RGK36 and RGK45) enhanced the cytotoxicity of ALA-PDT by regulation the expression of both PEPT1 and ABCG2." (PMID 31426474, 2019). "Our experimental study using gastric cancer cell lines suggested that upregulation of PEPT1 (ALA influx transporter) and downregulation of ABCG2 (porphyrin efflux transporter) genes could play pivotal roles in ALA-induced tumor specific PpIX accumulation." (PMID 28257041, 2017). "In the present study, following the intraperitoneal injection of 5-Fu into gastric cancer xenografts in nude mice, the HIF-2α, ABCG2 and Oct-4 mRNA and protein levels increased, indicating that the gastric cancer cells were exhibiting chemotherapy resistance to 5-Fu." (PMID 25452783, 2015). "This showed that the combined use of 5-Fu and celecoxib is able to attenuate the resistance to chemotherapy in gastric cancer and enhance the effect of chemotherapy by reducing the expression of HIF-2α, ABCG2 and Oct-4 and cancer stem cells in tumor tissue xenografts in nude mice." (PMID 25452783, 2015). "To explore how BATF2 heightens the responsiveness of gastric cancer cells to 5-Fu therapy, we performed whole-transcriptome sequencing which suggested a link between BATF2 and the ATP-binding cassette transporter, pinpointing ABCG2 as a key downstream target influenced by BATF2." (PMID 39629124, 2024). "Likewise, in gastric cancer, GLI1 protein was found to up-regulate the expression of ATP-binding cassette sub-family G member 2 (ABCG2) via the interaction between Gli-binding consensus site and promoter fragment of ABCG2, thus changing cytochemical resistance." (PMID 34659557, 2021). "While, effects of ABCG2 on human gastric cancer (GC) has not been illustrated thoroughly." (PMID 28029654, 2017). "The mechanism associated with the amelioration of resistance to chemotherapy in gastric cancer and the enhancement of the effect of chemotherapy may be via the reduction of the expression of HIF-2α, ABCG2, Oct-4 and other cancer stem cell markers in the tumor tissues." (PMID 25452783, 2015).
prostate carcinoma (45 papers, 2011 to 2025). A carcinoma that arises from epithelial cells of the prostate gland. "The Multi Drug Resistance (MDR) gene, ABCG2, previously shown to cause resistance to docetaxel in prostate was regulated by ERβ2 and ERβ5 in three different prostate cancer cell lines." (PMID 30555629, 2018). "ABCG2 is also associated with multidrug resistance of prostate cancer." (PMID 35342431, 2022). "ABCG2 has earlier been shown to cause chemotherapy resistance in prostate cancer." (PMID 30555629, 2018). "Additionally, BCRP (also known as ABCG2), a stem cell marker, is associated with prostate cancer." (PMID 39519572, 2024). "In contrast, prostate cancer tissues exhibited frequent deep deletions in ABCG2, ABCG1, ABCC4, ABCA2, ABCC2, ABCC7/CFTR, and ABCC9." (PMID 40641097, 2025). "In prostate cancer tissues, however, gene amplifications and deep deletions were most frequently detected in ABCG2 and ABCG1." (PMID 40641097, 2025). "Midkine’s down-regulation in prostate cancer cells treated with quercetin inhibited stem cell proliferation in a dose-dependent matter by reducing the expression of p38, ABCG2, and NF-κB proteins." (PMID 39859345, 2025). "Natarajan and coworkers (2012) observed that prostate cancer cell line 22RV1 is resistant to paclitaxel, methotrexate, and doxorubicin due to high BCRP and ABCG2 expression levels." (PMID 39003454, 2024). "The ABCG2 protein expression level between normal samples and breast, lung, testis, and prostate cancer samples was validated using The Human Protein Atlas." (PMID 36555598, 2022). "ABCG2+/AR+ prostate cancer stem cells can survive under castration, chemotherapy, and hypoxia environment." (PMID 35342431, 2022). "Eggmanone treatment dramatically down-regulated CSC markers Nanog and ABCG2 as well as inhibited the sphere formation in the chemo-resistant prostate cancer DU-145-TXR and PC3-TxR cells." (PMID 34066000, 2021). "The transporter proteins ABCG2 and MDR1 cause chemotherapy resistance in prostate cancer, where both genes were shown to be increased during hypoxia and are direct targets of HIF-1α." (PMID 30555629, 2018). "ABCG2 is ATP binding membrane transporters, and is related to prostate cancer multi-drug resistance." (PMID 27447616, 2016). "This phenomenon has been studied most extensively in the prostate cancer, where ABCG2 is highly expressed in a small population of stem-like cancer cells and is able to regulate the efflux of androgen." (PMID 26714461, 2015). "Moreover, ABCG2 expression was higher in specimens from patients with prostate cancer that recurred post-radiation." (PMID 40282462, 2025). "Similarly, CD117+/ABCG2+ cells isolated from 22Rv1 prostate cancer cells overexpress the core stem cell transcription factors, Nanog, Oct3/4, and Sox2, and the CSC marker CD133." (PMID 35800367, 2022). "However, all this evidence indicated that ABCG2 maintains the characteristics of AR+ prostate cancer stem cells." (PMID 35342431, 2022). "So, ABCG2 can be used as a functional marker to target prostate cancer stem cells." (PMID 35342431, 2022). "It seems that ABCG2 as a specific marker of prostate cancer stem cells is still controversial." (PMID 35342431, 2022). "One mechanism of chemotherapy resistance was expression of the hypoxia-regulated, drug transporter genes, where especially ABCG2 and MDR1 were shown to be expressed in recurrent prostate cancer and to cause chemotherapy resistance by efficiently transporting drugs like docetaxel out of the cells." (PMID 30555629, 2018). "ABCG2 expression may correlate to worse prognosis in prostate cancer, partly by its correlation to cancer stem cells and partly by its ability to cause chemotherapy resistance." (PMID 30555629, 2018). "ABCG2 has been suggested as a biomarker for treatments targeting on prostate cancer stem cells." (PMID 27447616, 2016).
prostate carcinoma (continued). "After castration, ABCG2+/AR− prostate cancer stem cells could be isolated from prostate cancer tissues, and it is suggested that ABCG2 expression might protect prostate cancer stem cells from castration, chemotherapy and hypoxic environment." (PMID 27447616, 2016). "Interestingly, ILs-3, 6 and 11 significantly promoted colony formation and increased the expression of SOX2, CD44 and ABCG2 in both prostate cancer cell lines." (PMID 26528857, 2015). "Indeed, it was recently reported that, for prostate cancer patients with docetaxel treatment, ABCG2 rs2231142 correlates with improved drug response, but also correlates with poorer outcomes possibly through increasing intratumoral folate levels and thereby enhancing tumor cell proliferation." (PMID 33531973, 2021). "However, a number of reports have identified two areas of interest where ABCG2 may be functionally relevant in regards to CSCs and therapeutic response: in castration-resistant prostate cancer, and in radiation resistant cancer cells." (PMID 26714461, 2015). "In the prostate cancer cell line PC-3, both the ABCB1 (79%) and the ABCG2 (97%) promoter were highly methylated." (PMID 27689338, 2016). "PIM-1 increases the phosphorylation of ABCG2 at Thr362, and downregulation of PIM-1 increases the chemosensitivity of prostate cancer cells." (PMID 27596051, 2016). "Similarly, in prostate cancer, the alteration frequency varied from 1.1% in ABCG2 to 2.7% in ABCA2, with ABCG2 consistently showing the lowest level of genetic alterations in both cancer types." (PMID 40641097, 2025). "Results from the current study demonstrated that ABCG2, ALDH1A1, and Oct-4 genes are expressed heterogeneously in single cells isolated from the CWR-R1 prostate cancer cell line, a difference in gene expression would be hard to detect when analyzing bulk cells." (PMID 27785389, 2016). "Likewise, a robust decrease in the expression of CD338 (ABCG2), an ATP-binding cassette transporter, was also noted in 22RV1 shMALAT1 cells compared with 22RV1-shSCRM, suggesting that MALAT1 modulates stemness in prostate cancer cells." (PMID 37812088, 2023). "Finally, results demonstrate that the cells isolated based on the side- and non-side population phenotype from CWR-R1 prostate cancer cells have a heterogeneous expression of ABCG2, Oct-4, and ALDH1A1." (PMID 27785389, 2016). "Though none of these ABCG2-specific efforts have yet resulted in improvements in patient care, the broader concept of circumventing drug efflux pump-mediated resistance has led to the development and approval of cabazitaxel for prostate cancer." (PMID 26714461, 2015). "For instance, folate-targeted paclitaxel–fisetin nanoparticles downregulated ABCG2 and triggered apoptosis in resistant ovarian cells, whereas NanoOrl, an orlistat-loaded formulation, restored taxane sensitivity via fatty acid synthase inhibition, independent of P-gp in prostate cancer." (PMID 40806254, 2025). "Analysis of the expression of ABCG2, ALDH1A1, and Oct-4 genes in single side- and non-side population cells isolated from the CWR-R1 prostate cancer cell line was performed." (PMID 27785389, 2016). "Normal prostate cells express BCRP (ABCG2) and MRP (ABCC1) but not P-gp (ABCB1), whereas prostate cancer cells do express P-gp." (PMID 26587537, 2015).
acute myeloid leukemia (37 papers, 2009 to 2026). Acute myeloid leukemia (AML) is a group of neoplasms arising from precursor cells committed to the myeloid cell-line differentiation. "Since its first description in the late 1990s, several studies have associated ABCG2 overexpression with poor outcomes in acute myeloid leukemia." (PMID 38255216, 2024). "The Q141K polymorphism of the ABCG2 protein is related to poor outcome in adults with acute myeloid leukemia treated with idarubicin‐based chemotherapy, and Q141K‐ABCG2 is the most common variant among Caucasians." (PMID 37150853, 2023). "ABCG2-mediated efflux block was also demonstrated by venetoclax, bcl-2 inhibitors originally approved for lymphoproliferative diseases and recently employed in elderly acute myeloid leukemia in association with hypomethylating agents." (PMID 38255216, 2024). "ABCG2 is overexpressed in many solid tumors as well as acute myeloid leukemia (AML) and acute lymphocytic leukemia (ALL)." (PMID 33946618, 2021). "To date, several cis-regulatory elements and transcription factor binding sites in the ABCG2 gene region have been identified, many of them expressed in a tissue-specific manner, many of them overexpressed in acute myeloid leukemia, and often already targets of new anticancer molecules." (PMID 38255216, 2024). "Clinical evidence has shown that high expression of ABCB1 and/or ABCG2 is linked with the MDR phenotype in advanced NSCLC, metastatic breast cancer, acute lymphocytic leukemia (ALL), acute myelogenous leukemia (AML), chronic lymphocytic leukemia (CLL), and multiple myeloma (MM)." (PMID 37048130, 2023). "Increased ABCG2 gene expression has also been related to poor response to chemotherapy in childhood acute myeloid leukemia (AML) and relapsed AML." (PMID 26515463, 2015). "In FLT3-ITD acute myeloid leukemia, the combination of homoharringtonine and quizartinib AKT and its downstream targets, including c-MYC, reduces the ABCG2 overexpressing side population." (PMID 38255216, 2024). "In this paper, we focused on ABCG2, one of the most recently identified components of the ABC superfamily, revising the current knowledge on its expression and prognostic role in acute myeloid leukemia and on the possible methods for reverting its activity." (PMID 38255216, 2024). "A clinical study performed in 2006 to evaluate the gene expression of adult acute myeloid leukemia (AML) showed high MDR1/ABCB1 and BCRP/ABCG2 expression in a subset of patients with the worst overall survival and high drug resistance." (PMID 34208283, 2021). "High levels of ABCG2 expression were also present in acute lymphoblastic leukemia (ALL) and acute myelogenous leukemia (AML)." (PMID 25268163, 2014). "Corroborating these data, it has been recently described that co-culture with mesenchymal stromal cells from bone marrow induced increased activity of ABCB1, ABCG2 and ABCC1 with the development of an SP phenotype from blasts of acute myeloid leukemias obtained from human patients." (PMID 37047018, 2023). "In acute myeloid leukemia, as well as in many other cancer types, a recognized role in affecting the initial response to chemotherapy has been attributed to the efflux pump activity of the tree most studied members of the ABC protein family, ABCB1, ABCC1, and ABCG2." (PMID 38255216, 2024). "In both acute myeloid leukemia (AML) and acute lymphoblastic leukemia (ALL), activated PI3K upregulated ABCG2 expression and elevated percentage of cancer stem-like cells." (PMID 38365611, 2024). "In addition, a CRISPR/Cas9 KO of BEN domain-containing protein 3 (BEND3) upregulated efflux transporter breast cancer resistance protein (BCRP; ABCG2) and reduced the intracellular levels of TAK-243 and induced resistance in acute myeloid leukaemia (AML) cells." (PMID 35631480, 2022).
acute myeloid leukemia (continued). "Since ABCG2 is likely to be expressed in a small subset of acute myeloid leukemia cells with primitive characteristics, such as expression of CD34 but not CD38, the evaluation of ABCG2 and its inhibition should be focused on those cells." (PMID 25268163, 2014).
chronic myeloid leukemia (35 papers, 2012 to 2026). "For example, a meta-analysis of the association between ABCG2 421C>A polymorphism and imatinib response in patients with chronic myeloid leukemia revealed that the A allele was significantly associated with an increased rate of overall response." (PMID 35335877, 2022). "Intracellular accumulation of erlotinib was assessed in the chronic myeloid leukemia cell line, K562, stably transduced with ABCG2 wt, the ABCG2 polymorphisms 34 G > A and 421 C > A, and empty vector." (PMID 32266784, 2020). "It was reported that reduced ABCG2 and increased SLC22A1 mRNA expression are associated with imatinib response in chronic myeloid leukemia 54, and simultaneous high expressions of SLC31A1 and ABCG2 are associated with poor survival of HNSCC patients." (PMID 33531973, 2021). "Correlations between ABCG2 expression and decreased survival and response to therapy have been identified, including dasatinib response in chronic myeloid leukaemia." (PMID 31530935, 2020). "Reports started with ABCB1 and ABCG2 overexpression in Philadelphia chromosome-positive chronic myeloid leukemia cells as a consequence of imatinib selection." (PMID 27367030, 2016). "In chronic myeloid leukemia K-562 cells, short-term imatinib treatment induced ABCG2 expression and decreased miR-212 expression, while anti-miR-212 upregulated ABCG2 protein expression by direct targeting ABCG2 3’-UTR." (PMID 27834829, 2016). "This study aimed to explore the influence of SLC22A1, PXR, ABCG2, ABCB1 and CYP3A5*3 genetic polymorphisms on imatinib mesylate (IM) pharmacokinetics in Asian patients with chronic myeloid leukemia (CML)." (PMID 23272163, 2012). "High expression of ABCG2 in premature chronic myeloid leukemia cell populations has been reported." (PMID 25268163, 2014). "In particular, elacridar effectively potentiated the cytotoxic and anti-proliferative activities of imatinib mesylate against chronic myeloid leukemia (CML) cells overexpressing ABCB1 and ABCG2." (PMID 41154409, 2025). "Tyrosine Kinase Inhibitors (TKIs), like nilotinib and dasatinib, are effective treatments available for Chronic Myeloid Leukaemia (CML) and found to interact with ABCB1 and ABCG2." (PMID 33799762, 2021). "Transmembrane transporters from the ATP Binding Cassette (ABC) superfamily ABCB1 (MDR1), ABCC1, ABCG2 are involved in the acquired resistance in AML, acute lymphocytic leukemia (ALL) and chronic myeloid leukemia (CML)." (PMID 34683897, 2021). "In chronic myeloid leukemia, miR-212 inhibition resulted in ABCG2 (ABC Subfamily G Member 2) upregulation and increased ABCG2-dependent efflux of Imatinib." (PMID 34072348, 2021). "In CD34+ chronic myeloid leukemia (CML) hematopoietic progenitor cells, ABCG2 expression is positively regulated by MYC." (PMID 29186899, 2017). "The chronic myeloid leukemia K562 cell line, neither expressing EGFR nor ABCG2, was transduced with vectors containing the ABCG2 wt, the SNPs: 34 G > A and 421 C > A, or with empty vector (K562/ve)." (PMID 32266784, 2020).